IL1B (interleukin 1 beta)
Diseases named in the same sentence as IL1B in open-access papers (continued):
Sharing a sentence is not in itself a finding about the gene and the disease.
lung carcinoma (continued). "In this study, we revealed that ectopic expression of miR-19a or miR-19b-1 modulated the expression of IL-related genes (including IL1B, IL11RA, IL20RB, IL6 and IL32) and suppressed IL6 production in lung cancer and NPC cells." (PMID 32308549, 2020). "Human lung cancer cells release microparticles that bind TLR3 to trigger NLRP3 inflammasome pathways in macrophages and IL-1β secretion." (PMID 32635472, 2020). "In this study, we found that human lung cancer cell-released MPs trigger the TLR3 and NLRP3 inflammasome pathways in macrophages, leading to the secretion of IL-1β." (PMID 31649305, 2020). "Baseline biomarkers of inflammation (IL-1b and neutrophil count) and early-treatment tumor burden (CYFRA 21-1) predict for survival in lung cancer patients treated with radiotherapy." (PMID 29398577, 2018). "•Baseline IL-1b and neutrophil count and early-treatment CYFRA 21-1 predict lung cancer radiotherapy response." (PMID 29398577, 2018). "We examined expression of IL-1A, IL-1B, IL-6 and IL-8 in two pairs of gefitinib-sensitive (PC9, and HCC827) and gefitinib-resistant (PC9/gef, and HCC827/gef) lung cancer cell lines to identify the specific cytokine involved in gefitinib resistance by RT-qPCR." (PMID 25871388, 2015). "Weight loss, lean body mass decrease, and hypermetabolism are highly correlated to both the elevated levels of proinflammatory cytokines, such as IL-1β, IL-6 and TNF-α and the decreased level of albumin in lung cancer patients." (PMID 23349693, 2013). "Treatment of A549 lung cancer cells with the COX-2 gene activators, PMA, IL1β and TNFα increased levels of COX-2 protein, mRNA and promoter RNA." (PMID 23999091, 2013). "Five altered cytokines in stage I lung cancer patients (CCL3, IL8, IL1β, CXCL10, sIL2Rα) were identified in plasma from subjects (n = 15) before and after resection using a 30-plex panel protein assay." (PMID 23762239, 2013). "The mean expression in lung cancer patients was significantly higher relative to controls for CCL3 and IL1β (10 and 29 fold, respectively)." (PMID 23762239, 2013). "There is also a known correlation between IL-1β and the induction of EMT in lung cancer." (PMID 41148809, 2025). "Indeed, a causal role of IL-1β in NSCLC has been implicated from a phase III clinical trial showing that treatment with canakinumab, a human monoclonal antibody specific for IL-1β, reduced NSCLC incidence and lung cancer mortality in a dose-dependent manner." (PMID 40794443, 2025). "GGT1 is highly expressed in the A549 lung adenocarcinoma cell line and its expression increases after IL‐1β stimulation, which rapidly converts LTC4 to LTD4, and GGT1 shows an important role in the development of resistance to erlotinib in non‐small cell lung cancer (NSCLC) cells." (PMID 41316810, 2025). "As they may pertain to patients, our data illuminate the therapeutic window for anakinra therapy during lung cancer progression, which appears analogous to results from phase III trials that sought to test the therapeutic potential of IL-1β blockade." (PMID 39236155, 2024). "Although the mechanism by which PM2.5 causes lung cancer is not clear, in mice, inhalation of PM2.5 induces an inflammatory axis driven by IL1B, which is associated with the development of lung cancer." (PMID 39516640, 2024). "Clinical trials with canakinumab, an IL‐1β monoclonal antibody, have been conducted in lung cancer; however, the CANOPY‐1 phase III clinical trial has not shown a survival benefit." (PMID 38798075, 2024). "IL-1α blockade delayed lung cancer progression more robustly than IL-1β blockade; notably, though, the combination of both exhibited an apparent synergistic effect in reducing tumor growth that was comparable to treating mice with anakinra." (PMID 39236155, 2024). "However, in AMs of lung cancer patients, NLRP3 inflammasome activation is decreased, and IL-1β secretion is decreased." (PMID 39420831, 2024).
lung carcinoma (continued). "The involvement of IL1B—one of the 16 common genes identified in this study—in this mechanism has not been elucidated in both breast and lung cancer development and progression." (PMID 38982523, 2024). "While clinical studies with COX-2 or IL-1B inhibitors have shown benefit in preventing the development of colon and lung cancers, respectively, there is not yet evidence that these agents have an impact on established cancers, even when combined with ICB." (PMID 38443917, 2024). "The levels of inflammatory factors such as IL-1β, IL-6, TNF-α, and CRP in the serum of the lung cancer mice increased, promoting the activation of inflammatory cells and stimulating the release of inflammatory mediators, leading to an increased risk of systemic inflammatory response." (PMID 39594117, 2024). "F. persica and its main constituent coumarin are shown as a possible treatment for lung cancer via the inhibition of cyclins and CDK, their reducing effects on cancer cell migration and metastasis mediated by cytokines such as IL‐1β, oxidative marker production, cell viability and cytotoxicity." (PMID 37697969, 2023). "IL-1β has been found to contribute to tumor progression by promoting the secretion of matrix metalloproteinases (MMPs) and hepatocyte growth factor (HGF) in lung cancer." (PMID 37772231, 2023). "However, it has been reported that SOR reduces JNK expression in lung cancer cell lines in vitro, and it has therapeutic properties by reducing TNF-α and IL-1β levels in liver cancer." (PMID 37259369, 2023). "High expression of the BC-specific ICD-derived metagene signature (TNF/CXCR3/P2RX7/CASP1/NLRP3/IL1B/LY96/CD4+/CD8+A/CD8+B/PRF1/IFNG/IL17A/IL17RA) is associated with prolonged overall survival (OS) in BC and OC patients but not in lung cancer patients." (PMID 37445860, 2023). "Notably, among them (IL1-β, IL-3, MCP-1, TNF-α), the EGF, the most acknowledged target for lung cancer therapy, emerges." (PMID 36733673, 2023). "In contrast, IL-1β treatment of lung cancer cells, which induces a mesenchymal-like morphology, does not upregulate fibronectin." (PMID 36922898, 2023). "Then, the migration and invasion of lung cancer cells were detected with miR-223-3p mimic and inhibitor using Transwell assay, at the same time the expression of NLRP3, cleaved caspase-1, IL-1β and IL-18 was determined using Western Blot and immunohistochemistry assay." (PMID 36276078, 2022). "This study aimed to explore the value of serum interleukin-1β (IL-1β), interleukin-6 (IL-6), and interleukin-8 (IL-8) combined with carcinoembryonic antigen (CEA) as biomarker panel for the diagnosis and metastasis prediction of lung cancer." (PMID 35928100, 2022). "Moreover, in lung cancer, previous studies have shown that NLRP3 can enhance the proliferation of A549 cells through IL-1β/ERK/CREB and IL-18/AKT/CREK signaling pathways, and promote tumor metastasis by reducing E-cadherin and increasing Snail expression." (PMID 36349316, 2022). "Thus, reducing IL-1β expression and increasing TNF-α level demonstrated amplified cytotoxicity against lung cancer cell lines." (PMID 34883728, 2021). "The relationship between IL-1β and lung cancer has not been well-defined in the context of tumor microenvironment." (PMID 33686176, 2021). "For example, meroterpenoids, isolated from the brown seaweed Cystoseira usneoides, significantly reduced the production of TNF-α, IL-6, and IL-1β, suppressed COX-2 expression, and displayed higher cytotoxic activities against lung cancer cells compared with normal lung cells." (PMID 33537234, 2020). "Significantly elevated expression of IL1-β, IL-6, IL-8, IL-10, IL-17, TNF-α, TGF-β, IFN-γ, and C-X-C motif chemokine ligand 1 (CXCL1) has been seen in colorectal cancer and other solid cancers like lung cancer." (PMID 32425932, 2020).
lung carcinoma (continued). "In the present study, our data support the notion that M-CSF secreted by Oct4-overexpressing lung cancer cells, which can be upregulated, in part, by TNF-α and IL-1β secreted from M1 macrophages, promotes Oct4-mediated M2 macrophage polarization and thereby increases tumor progression." (PMID 32487125, 2020). "This release of IL-1β by macrophages exerts a tumor-promoting effect, which may help explain target therapy-related tumor progression in EGFR mutant lung cancer patients." (PMID 31649305, 2020). "This was based on a significant reduction of lung cancers in the CANTOS trial on 10,061 patients with cardiovascular disorders and high C‐reactive proteins (CRPs) who were randomized to placebo or different doses of canakinumab, an antibody against IL‐1β." (PMID 32027447, 2020). "Consistently, reduced NLRP3-dependent IL-1β secretion is observed in AMs isolated from the bronchoalveolar lavage of lung cancer patients despite a systemic higher NLRP3 inflammasome activation and IL-1β secretion in peripheral blood leukocytes from these patients." (PMID 30832375, 2019). "Similar to NF-κB, IL-1β and oxidative stress are usually prominent in cancer cells, but the upregulation of miRNA-146a by these factors cannot explain the high expression of CFH in lung cancers." (PMID 30987235, 2019). "USP17 could be induced by cytokines secreted from macrophages because various cytokines, including TNF-α, IL-1β, IL-4, IL-6, IL-8, IL-10, CXCL12, CCL18, and CCL22, were able to induce USP17 expression in H1299 and D121 lung cancer cells." (PMID 30038267, 2018). "Control and USP17-overexpressing H1299 and D121 lung cancer cells were treated with or without IL-1β." (PMID 30038267, 2018). "Of note, also the expression levels of other putative tumor-derived cachexia-inducing signaling compounds (OSM, LIF, TNFα, IFNγ, PTHrP, ZAG, PIF, TWEAK, IL-1β, MSTN and INHBA) were tested for possible correlation between expression level and prognosis for lung cancer patients." (PMID 28515477, 2017). "In summary, our findings demonstrate that IL-1β, in concert with other unknown co-stimulating factors, induces IL-33 in ST2L-positive low-metastatic lung cancer cells." (PMID 26775708, 2016). "Mechanistically, the lung cancer-promoting effect of HDM was primarily attributed to the chronic activation of the Nod-like receptor family pyrin domain-containing protein 3 (NLRP3) inflammasome in lung macrophages, leading to persistent IL-1β production in the lungs." (PMID 41445736, 2025). "IL-1β blockade with chemotherapy or immunotherapy may not be the most effective modality in lung cancer treatment." (PMID 40940992, 2025). "Additionally, exposure to IL-1β decreases phosphatase and tensin homolog (PTEN) expression, subsequently activating phosphatidylinositol 3-kinase/protein kinase B (PI3K/AKT) signalling and inducing EMT in lung cancer." (PMID 41148809, 2025). "Although the effect of Sch B on IL-1β has seldomly been observed in cancer models, its inhibitory effect on nuclear factor kappa-light-chain-enhancer of activated B cells (NF-ĸB), the central mediator of the priming signal of NLRP3 inflammasome, has been investigated in lung cancer cell lines." (PMID 38254674, 2024). "Evidence suggests that cytokines such as interleukin-1β (IL-1β), IL-6, interleukin-7 (IL-7), interleukin-8 (IL-8), interleukin-11 (IL-11), tumor necrosis factor-alpha (TNF-α), TGF-β, and C-C motif chemokine ligand 12 (CCL12) play significant roles in the bone metastasis of lung cancer." (PMID 38571500, 2024).
lung carcinoma (continued). "In addition, in a subcutaneous tumor model of lung cancer in mice, we observed that NLRP3 inflammasome and downstream IL-1β could promote tumor angiogenesis and lymphangiogenesis, as well as tumor growth." (PMID 39230586, 2024). "Furthermore, we examined whether IL1β and IL18, which are the downstream mediators of the NLRP3 inflammasome, can promote the proliferation of lung cancer cells." (PMID 37524704, 2023). "Similarly, 4-hydroxybenzoic acid selectively induces pyroptosis in lung cancer cell line A549 through activating transcription of caspase-1, IL-1β, and IL-18, while normal lung epithelial cells are not affected." (PMID 36932407, 2023). "In addition, the use of serum interleukin-1β (IL-1β), interleukin-6 (IL-6), and interleukin-8 (IL-8) in combination with carcinoembryonic antigen (CEA) as a biomarker panel for the detection and prediction of lung cancer metastasis are being studied." (PMID 36874133, 2023). "GATA2, a transcription factor directly known to regulate the IL-1β signaling pathway, has been shown to function as a link between IL-1β signaling and tumor cell proliferation, since GATA2 genetic depletion diminishes tumor burden and progression in K-ras-induced lung cancer models." (PMID 32039025, 2019). "In addition, studies have found that IL-1β promotes the invasion and metastasis of lung cancer A549 cell line, thereby promoting the progression and metastasis of cancer, and TNF-α could promote the metastasis of lung cancer by inducing EMT." (PMID 35449557, 2022). "Our data indicated that IL‐1β could stimulate CCL20 production from lung cancer cells through the activation of MAPKs and PI3K signal pathways, and the auto‐secretion of CCL20 could promote lung cancer cell migration and proliferation through the activation of ERK and PI3K signal pathways." (PMID 26968871, 2016). "Conditioned media from MUFA-treated lung cancer cells appeared to suppress secretion of TNF-α, IL-1β, and MIP-1 cytokines from monocytes, but none reached statistical significance." (PMID 39100092, 2024). "In summary, our data showed that human lung cancer cell-derived MPs, due to their ability to carry unique noncoding RNAs, result in the activation of TLR3 and the subsequent pro-IL-1β production in macrophages." (PMID 31649305, 2020). "Taken together, the data suggest that healthy donor PBMCs increase their expression of CCL3, IL8 and IL1β (with little or no increases in CXCL10 and IL2Rα) when they are exposed to lung cancer cells (Figures 4and5)." (PMID 23762239, 2013). "While IL-6 seems to play a role in lung cancer development in both never-smokers and ever-smokers, the possibility that IL-1β and IFN-γ may play roles in the mechanism of lung cancer development in never-smokers cannot be ruled out." (PMID 38067398, 2023). "In addition, we were not able to detect any increase in other inflammatory cytokines (e.g., IL-1α, IL-1β, IFN-α, IL-8 and IL-18) from both healthy and lung cancer-derived PBMCs after S1P stimulation (data not shown)." (PMID 36010601, 2022). "Although the data demonstrate that exposure of healthy donor PBMCs to lung cancer cell lines increases CCL3, IL8 and IL1β production by CD3+ and CD14+ PBMC fractions, it remains unclear as to the specific interaction which causes this result." (PMID 23762239, 2013). "Intracellular CCL3, IL8 and IL1β were detected in the CD3+ fraction (T cells) of healthy donor PBMCs which had been co-cultured with either lung cancer cell line, but not in those cultured in the absence of lung cancer cells." (PMID 23762239, 2013). "In the analysis, the histological lung cancer specimens from non-surviving patients displayed a distinct proinflammatory profile characterized by significantly higher levels of CD68 (macrophages) and IL-1β scores than the samples isolated from surviving patients." (PMID 35884397, 2022).
pulmonary fibrosis (278 papers, 2005 to 2026). Chronic progressive interstitial lung disorder characterized by the replacement of the lung tissue by connective tissue, leading to progressive dyspnea, respiratory failure, or right heart failure. "This study confirmed that LPS-induced pulmonary fibrosis is associated with pyroptosis and that LPS can promote the expression of the pyroptosis-related factors Caspase1, Gasdermin D and IL-1β." (PMID 38875245, 2024). "For instance, macrophage-derived molecules such as CXCL2, CCL2, and IL-1β have been linked to the progression of Idiopathic Pulmonary Fibrosis." (PMID 39866843, 2024). "Interleukin-1β (IL-1β), a crucial pro-inflammatory cytokine implicated in lung fibrosis, increases ITGB8 expression in the lung fibroblasts, which increases αvβ8-mediated TGFβ activation in fibrosis and pathologic inflammation." (PMID 39684311, 2024). "Recently, we reported that IL-1β, which is released from macrophages stimulated with nanoparticles that cause pulmonary fibrosis, can induce EMT in alveolar epithelial cells." (PMID 39118068, 2024). "CD36-null cells have increased expression of LPL, IL-6 and IL1-β which have been implicated in inflammasome assembly during bleomycin induced pulmonary fibrosis." (PMID 38098035, 2023). "IL-1β is a family member of interleukin-1 (IL-1), possessing pro-inflammatory effects and associated with pulmonary interstitial fibrosis." (PMID 36769382, 2023). "The age‐associated increase in lung fibrosis and inflammatory cytokines, including IL‐1β and TGF‐β1 that are highly expressed in bronchial epithelium, AT2 cells, and fibroblasts, are ameliorated in arg‐ii deficient (arg‐ii−/−) mice." (PMID 36794355, 2023). "Earlier studies have documented the pro-inflammatory cytokines overexpression being associated with BLM induced lung fibrosis in animal models, including IL-1β, IL-6 and TNF-α." (PMID 35326173, 2022). "IL-1β deficiency significant attenuates the pulmonary fibrosis induced by bleomycin in mice through relieving fibroblast–myofibroblast differentiation and the myofibroblasts longevity, which are also the critical events in skin fibrosis in SSc patients." (PMID 36532023, 2022). "IL-1β plays an important role in the pathogenesis of pulmonary fibrosis by inducing overexpression of TGF-β1, which, in turn, causes a progression to fibrosis via fibroblast differentiation and activation into myofibroblasts." (PMID 34306796, 2021). "Inflammatory cytokines, including TNF-α and IL-1β, and immune cells, including neutrophils, are important causes of pulmonary fibrosis." (PMID 35115954, 2021). "IL‐1β has also been implicated in the development of a number of respiratory diseases such as chronic obstructive pulmonary disease, silicosis and idiopathic pulmonary fibrosis." (PMID 33834544, 2021). "Nonetheless, it is worth reminding that IL-1β has been negatively implicated with pulmonary fibrosis as part of the pathologic role of chronic inflammation." (PMID 33182538, 2020). "In murine models of lung fibrosis, IL-1β has been associated with collagen deposition, while IL-1β receptor blockage reduces pulmonary fibrosis caused by silica or bleomycin." (PMID 32256366, 2020). "Both nintedanib and pirfenidone have been shown to inhibit lung fibrosis in murine models, and these effects were associated with a reduction in IL-1β levels in lung tissue." (PMID 27001429, 2016). "Inflammasome activation and increased IL-1β have been implicated in the pathogenesis of pulmonary fibrosis." (PMID 26091108, 2015). "In our model, 17(R)‐RvD1 protected against BLM‐induced pulmonary fibrosis by downregulating transcription of mRNAs encoding IL‐1β in the lungs." (PMID 26660549, 2015). "Previous reports demonstrate that MWCNTs cause inflammasome activation and subsequent IL-1β release by mononuclear cells to an extent similar to that of asbestos, a known cause of lung fibrosis." (PMID 25216247, 2014).